APOE (apolipoprotein E)
Diseases named in the same sentence as APOE in open-access papers (continued):
Sharing a sentence is not in itself a finding about the gene and the disease.
hippocampal atrophy (106 papers, 2007 to 2026). "MRI revealed hippocampal atrophy and leukoaraiosis; the presence of the ApoE E3/E4 risk genotype and vascular risk factors supported a diagnosis of mixed dementia, that is, AD with a prominent vascular component." (PMID 41551043, 2025). "Additional to age, factors such as female sex and APOE status are among the highest risk factors for sporadic AD and are therefore of high interest when studying hippocampal atrophy rates." (PMID 40741045, 2025). "Age and sex were significant covariates for the synaptic factor, whereas sex, education, and ApoE-ε4 carrier status were significantly associated with hippocampal atrophy in the model with YKL-40." (PMID 41442069, 2025). "Individuals with apolipoprotein E ε4, a well-established genetic risk factor for AD, were associated with high sedentary time and demonstrated faster hippocampal atrophy and decline in naming and information processing speed despite being physically active." (PMID 41092385, 2025). "Temporal atrophy was exacerbated in women, while frontal, lateral-temporal and hippocampal atrophy was exacerbated by carriership of at least one APOE-ε4 allele, with volumetric loss more sensitive to sex effects and thinning more sensitive to APOE-ε4 effects." (PMID 41270680, 2025). "The APOE ε4 allele (rs769449, rs439401 identified by the proposed model) is strongly associated with hippocampal atrophy." (PMID 40191788, 2025). "The APOE genotype distribution, hippocampal atrophy grades, and associated medical conditions were also reported." (PMID 38256652, 2024). "Clinical-pathologically, presence of the apolipoprotein E (APOE)-ε4 allele is the most well-known genetic factor that leads to hippocampal atrophy (HA), which is crucial in encoding and retrieving new information." (PMID 31164996, 2019). "Further recent findings also provide evidence that APOE-ε4 is linked to hippocampal atrophy and learning/memory phenotypes across the AD/DLB spectrum." (PMID 31024418, 2019). "The APOE e4 allele has been found to be associated with typical AD; memory problems, targeted hippocampal atrophy, and greater burden of AD pathology present in the hippocampus at autopsy." (PMID 29220823, 2018). "Taken together, we propose that the KIBRA T allele affords carriers a level of resilience to the detrimental effects of Aβ-amyloid and APOE ε4 allele on neurodegeneration, specifically hippocampal atrophy." (PMID 29391469, 2018). "Several previous studies have also found that TOMM40 is associated with hippocampal atrophy and decline in cognitive performance, independently of APOE." (PMID 30517207, 2018). "Some reported significant evidence of an association between APOE genotype and bilateral hippocampal atrophy rate." (PMID 24878738, 2014). "The current study reveals an effect of the APOE ε4 allele for greater hippocampal atrophy in subjects with a diagnosis of MCI or AD as compared to individuals without the ε4 allele in these diagnostic cohorts." (PMID 23405083, 2013). "The APOE ɛ 4 allele is a risk factor for lateonset Alzheimier disease, hippocampal atrophy, and senile plaques." (PMID 17431502, 2007). "A typical patient may present with both Alzheimer-type changes, such as hippocampal atrophy associated with APOE ε4 status, alongside vascular lesions on MRI, thereby meeting criteria for mixed Alzheimer-vascular dementia." (PMID 40970035, 2025). "However, at an uncorrected level, APOE ε4 was associated with a higher degree of hippocampal atrophy with increasing age (βwl = −0.011, edf = 1, punc = 0.01; βwr = −0.009, edf = 1, punc = 0.04, respectively)." (PMID 41271752, 2025). "There have also been reports that APOE ε4 causes earlier age of symptom onset, faster ventricular expansion, and greater rates of hippocampal atrophy and cortical thinning in subjects with MCI." (PMID 38318196, 2023).
hippocampal atrophy (continued). "In addition, APOE-ε4 being linked to hippocampal atrophy and learning/memory phenotypes across the AD/DLB spectrum, it highlights once more the relationship between olfactory dysfunction and cognitive condition." (PMID 35377902, 2022). "As previously noted, the memory-impaired subtypes of MCI had the greatest degree of hippocampal atrophy and were associated with an increased APOE-4 allele prevalence, which indicates a likelihood that these individuals will also be at risk for subsequent progression to AD." (PMID 35492717, 2022). "In respect to APOE genotyping, several studies suggested that the presence of an APOEε4 allele is related to longitudinal changes in medial temporal cortical thickness, and hippocampal atrophy rates." (PMID 31316372, 2019). "APOE is the best established and strongest risk factor for sporadic AD and has been associated not only with increased risk per se, but also with earlier disease onset, the rate of hippocampal atrophy and more memory led disease." (PMID 26993346, 2016). "To explore whether the presence of the APOE e4 allele was associated with greater hippocampal atrophy, we studied the effects of APOE e4 genotype in three follow up full ADNI cohorts." (PMID 27065111, 2016). "To better understand the effect of the APOE ε4 allele on the progression of structural brain changes we wanted to investigate whether different whole-brain and hippocampal atrophy rates were observed in ε4+ compared with ε4- in AD, MCI and controls." (PMID 24878738, 2014). "However, in the obese BMI ranges (30 kg/m2), AD genetic susceptibility conferred by the APOE-ε4 allele may compound the risk for hippocampal atrophy in this population." (PMID 37731955, 2023). "While the potential interaction between Aβ burden and APOE ε4 in determining hippocampal atrophy trajectories was beyond the scope of this study, it warrants further investigation in future research." (PMID 39898436, 2025). "For instance, we observed two extreme subtypes characterized by highly focal hippocampal atrophy and preserved brain volume, showing significantly differences in rs429358 (APOE) with the highest and lowest EAFs, respectively." (PMID 38191573, 2024). "After adjusting for age, sex, imaging system type, and APOE 4 genotype, cognitively normal control subjects with CSF markers in the upper tercile had higher rates of whole-brain and hippocampal atrophy compared to those with lower levels of CSF markers." (PMID 39210976, 2024). "Several studies also find that sex modulates the interactions between amyloid SUVR and brain volume change, between CSF biomarkers and hippocampal atrophy and between APOE genotype and hippocampal atrophy." (PMID 37333001, 2023). "We found that APOE ε4 accelerates the longitudinal hippocampal atrophy in both full cohort and matched sub-samples." (PMID 37323144, 2023). "The current investigation confirms prior work linking elevated BPV to hippocampal atrophy and extends findings by identifying the key role of APOE ε4 in determining the relationship between BPV and both hippocampal and entorhinal cortical atrophy." (PMID 34581957, 2022). "Recent investigations indicate that APOE-ε4 is related to hippocampal atrophy along with learning and memory performance in DLB as well as across the AD/DLB spectrum, implicating APOE-ε4-associated shared neurodegenerative mechanisms across these disorders." (PMID 33178113, 2020). "We note that among the top 5 features are the 2 ADNI cognitive performance variables, the plasma analytes Apolipoprotein E and C Reactive protein, as well as right hippocampal atrophy rate." (PMID 32716914, 2020). "Our current findings, supported by some prior work, identified that APOE-e4 carriers of cognitively unimpaired subjects had significant left hippocampal atrophy." (PMID 30852398, 2019).
hippocampal atrophy (continued). "Regarding the effect of APOE-ABCA7 interactions on functional connectivity in the vDMN, previous studies have reported that the hippocampal atrophy is associated with ABCA7 rs3764650G allele and APOE-ε4 carriage." (PMID 31831047, 2019). "Female carriers of the APOE ε4 are more likely to develop AD and show significantly greater hippocampal atrophy." (PMID 28086184, 2017). "The mechanism by which APOE e4 may have its effects is currently unclear, but the presence of the allele has been linked to neural characteristics including reduced cerebral blood flow (Thambisetty, Beason-Held, An, Kraut, & Resnick, 2010), hippocampal atrophy, and a thinner frontal cortex." (PMID 27932854, 2016). "Only hippocampal atrophy progressed significantly faster in ApoE ε4 homozygote carriers." (PMID 41716658, 2026). "•APOE-ε4 carriers show larger Aβ-driven frontal & hippocampal atrophy." (PMID 41270680, 2025). "We speculate that APOC1 may contribute to cortical thinning and hippocampal atrophy through molecular mechanisms that differ from those of APOE." (PMID 40369256, 2025). "Integrative analysis using neuroimaging data and hippocampal TWAS-predicted gene expression of the three susceptibility genes showed an inverse correlation of SLC25A22 with hippocampal atrophy rate in AD patients, which outweighed the impacts of sex, age, and apolipoprotein E4 (ApoE4)." (PMID 38858380, 2024). "Elderly normal APOE ε2 carriers also exhibit slower rates of hippocampal atrophy." (PMID 35203950, 2022). "Additionally, some studies have reported that APOE ε2 carriers have lower levels of hippocampal atrophy in old age." (PMID 32961217, 2021). "ApoE ε4 status has been shown to have larger impact on memory performance and hippocampal atrophy in women than in men, and this network suggests that midlife cardiovascular mechanisms might be responsible for this relationship." (PMID 34267647, 2021). "The data reported here support the hypothesis that KIBRA genotype, in combination with APOE ε4 and Aβ-amyloid, affects rates of memory decline and hippocampal atrophy in cognitively normal adults." (PMID 29391469, 2018). "Younger age was also associated with greater hippocampal atrophy rate in MCI, in which a reduction in atrophy rate of 0.04 mL/y (0.02–0.06) for a 10 year increase in age was seen after adjusting for WMH and APOE e4 and subtracting the age-atrophy effect in controls." (PMID 29220823, 2018). "Higher levels of Cystatin C (CysC) were positively associated with all three atrophy measures after adjusting for baseline brain volumes and t-tau and remained predictive of higher whole brain (P=0.009) and hippocampal atrophy (P=0.034) after adjusting for p-tau, age, ApoE status and sex." (PMID 25072324, 2014). "One such facet that still remains uncertain is whether there is an effect of APOE genotype on structural brain changes seen in AD, such as hippocampal atrophy." (PMID 23405083, 2013). "We also found that both ε4 carriers and noncarriers with CN2D conversion presented faster accelerated hippocampal atrophy than ε4 carriers with persistent CN, indicating that APOE is not the only risk gene that contributes to the progressive hippocampal atrophy during CN2D conversion." (PMID 37323144, 2023). "In addition to supporting the established interaction between APOE and amyloid on neurodegeneration, our study identifies a novel locus that modifies the association between beta-amyloid and hippocampal atrophy." (PMID 35425899, 2022). "Our data indicated that APOE ε4 carriers as an at-risk population for AD may benefit from drug or non-drug interventions that are tailored to the levels of hippocampal atrophy." (PMID 30863302, 2019).
hippocampal atrophy (continued). "In contrast to controls, younger age was associated with greater hippocampal atrophy rate in AD patients, corresponding to a reduction in atrophy rate of 0.03 mL/y (0.05, 0.001) for a 10-year increase in age after adjusting for WMH and APOE e4 and subtracting the age–atrophy effect in controls." (PMID 29220823, 2018). "Numerous publications have attempted to elucidate whether APOE modifies hippocampal atrophy rates." (PMID 24878738, 2014). "The hypothesis was that CN adults who carry the rs17070145-T allele would show a slower rate of memory decline and hippocampal atrophy than those not carrying this allele, though this relationship would be dependent on the presence of a high brain Aβ-amyloid burden and interact with APOE genotype." (PMID 29391469, 2018). "Previous studies found that the APOE ε4 carriers have greater hippocampal atrophy than the non-carriers in patients with AD, cognitively normal elderly, and healthy young adults." (PMID 33603659, 2021). "Moreover, the prime factors contributing to hippocampal atrophy rate (HAR) includes age, gender, ApoE ε4 status, intracranial volume, white matter lesions and Aβ levels, and Aβ status is a significant predictor of HAR." (PMID 27177090, 2016). "There were no statistically significant between-group differences in the rate of hippocampal atrophy after stratification for APOE genotype (data not shown)." (PMID 25478019, 2014). "The objective of the current analysis was to assess the effect of galantamine (compared with placebo) on the rate of total brain and hippocampal atrophy, using serial MRI in individuals with MCI, and to assess whether this effect was modified by APOE genotype." (PMID 25478019, 2014). "In our study, the impact of mitochondrial genetic variation on hippocampal atrophy is independent of APOE ε4 status." (PMID 24040196, 2013). "Or expressed differently, keeping a healthy weight may not be sufficient to compensate for APOE ε4-driven hippocampal atrophy." (PMID 35303671, 2022). "Once AD pathological burdens sufficiently accrue (such as hippocampal atrophy), this APOE ε4 advantage was not evident and gradually reversed to confer memory deficits among subjects with moderate to small HpVR (HpVR < approximately 5.2, referring to the failure of compensatory recruitment)." (PMID 30863302, 2019).
myocardial infarction (106 papers, 2007 to 2026). Gross necrosis of the myocardium, as a result of interruption of the blood supply to the area, as in coronary thrombosis. "Depending on the allele of the APOE genotype, some researchers show apoE-associated increased cardiovascular risk, while others show a protective effect in, for example, myocardial infarction." (PMID 39769362, 2024). "Case–control studies on the association between APOE polymorphisms and the risk of myocardial infarction were included by searching PubMed, Web of Science, and CNKI, and this meta-analysis was written in accordance with PRISMA guideline statement." (PMID 35331149, 2022). "The present study aimed to analyze possible associations of rs7412 and rs429358 of the APOE gene with lipid profile parameters, the risk of myocardial infarction, and death in the mostly white population of Western Siberia (Russia)." (PMID 35723376, 2022). "In fact, hyperlipidemic ApoE-deficient mice have a higher risk of arrhythmia post-myocardial infarction than wild-type mice." (PMID 33271910, 2020). "According to previous studies, mice containing atherogenic mutations in ApoE–/– mice develop either spontaneous or high fat diet-induced coronary artery atherosclerosis, myocardial infarction, and dramatically reduced survival." (PMID 33330454, 2020). "In this study, we investigated the effect of ApoE deficiency on neutrophils' function and myocardial injury after myocardial infarction." (PMID 31249639, 2019). "To further verify that ApoE deficiency enhanced the mobilization of immune cells after myocardial infarction, we detected the ratio changes in the blood of both mice before ligation and 3 days and 7 days after ligation by FCM." (PMID 31249639, 2019). "The results demonstrated that apolipoprotein E deficiency played a causal role in the increased infiltration of neutrophils after myocardial infarction." (PMID 31249639, 2019). "To investigate the role of ApoE deficiency in myocardial infarction injury, we established myocardial infarction by permanent coronary artery ligation to both ApoE−/− and WT mice." (PMID 31249639, 2019). "On the other hand, beneficial effects of APOE ε4 allele have been reported in other human diseases, including myocardial infarction." (PMID 25085564, 2014). "APOE832/rs405509 located in the putative promoter region has previously been shown to be associated with LDL-related traits (LDL-C, TC, and ApoB), APOE gene expression, myocardial infarction risk, and premature CHD." (PMID 25502880, 2014). "SR-BI deficient mice that are also hypomorphic for apolipoprotein E expression develop diet induced occlusive coronary artery atherosclerosis, myocardial infarction and early death." (PMID 23967310, 2013). "We also confirmed the association between APOE polymorphism and risk of myocardial infarction reported by many others, especially for E4 genotypes." (PMID 21941641, 2011). "Previously, we had shown that PDZK1 deficiency enhances aortic root atherosclerosis in apoE deficient mice on a Western-type high fat/high cholesterol diet, but did not markedly induce occlusive coronary arterial atherosclerosis or myocardial infarction." (PMID 19956623, 2009). "ApoE deficiency in mice impairs infarct healing after myocardial infarction (MI)." (PMID 31249639, 2019). "Furthermore, in several of the TAC-induced ApoE−/− mice, evidence of myocardial infarction caused by embolism was obtained, which suggests the model could be used for studying no reflow caused by microemboli." (PMID 33258000, 2020). "In addition, cardiovascular diseases (heart attack and stroke) have been strongly linked to APOE." (PMID 30889929, 2019).